PCSK4 (proprotein convertase subtilisin/kexin type 4)
Description:
Proprotein convertase involved in the processing of hormone and other protein precursors at sites comprised of pairs of basic amino acid residues (By similarity). In males, important for ADAM2 processing as well as other acrosomal proteins with roles in fertilization and critical for normal fertilization events such as sperm capacitation, acrosome reaction and binding of sperm to zona pellucida (By similarity). Also plays a role in female fertility, involved in the regulation of trophoblast migration and placental development, may be through the proteolytical processing and activation of proteins such as IGF2. May also participate in folliculogenesis in the ovaries (By similarity).
Synonyms: PC4; SPC5; DKFZp434B217; MGC34749
Tractability: Antibody: UniProt predicts a signal peptide or a membrane-spanning region. PROTAC: a small molecule that binds it is known.
Target class: Enzyme; Serine protease S8B subfamily; Serine protease SB clan; Protease; Serine protease
Gene: Protein-coding gene on chromosome 19 (1,481,428 to 1,490,752, reverse strand). Ensembl gene ENSG00000115257.
Subcellular location: Membrane; Cytoplasmic vesicle, secretory vesicle, acrosome membrane
Gene Ontology:
Molecular function: protein binding; serine-type endopeptidase activity; serine-type peptidase activity
Biological process: protein processing; acrosome reaction; binding of sperm to zona pellucida; fertilization; peptide hormone processing; reproductive process; sperm capacitation; proteolysis
Cellular component: acrosomal membrane; acrosomal vesicle; Golgi membrane; trans-Golgi network; membrane
Genetic constraint (gnomAD): Loss-of-function variants: 63 observed, 65.86 expected, observed/expected ratio (o/e) 0.96, 90% interval 0.78 to 1.18. The synonymous counts are far from expectation, so gnomAD's model fits this gene poorly and the ratio says little. Missense variants: 1,162 observed, 914.7 expected, observed/expected ratio (o/e) 1.27, 90% interval 1.21 to 1.33. Synonymous variants: 542 observed, 406.13 expected, observed/expected ratio (o/e) 1.33, 90% interval 1.24 to 1.43.
Homologues: Orthologues: chimpanzee PCSK4 (87% identical), macaque PCSK4 (84% identical), pig PCSK4 (83% identical), dog PCSK4 (82% identical), mouse Pcsk4 (70% identical), guinea pig PCSK4 (67% identical), rat Pcsk4 (66% identical), tropical clawed frog pcsk4 (56% identical), Drosophila melanogaster Fur2 (45% identical), Caenorhabditis elegans kpc-1 (40% identical). Paralogues in human: FURIN (52% identical), PCSK5 (43% identical), PCSK6 (43% identical), PCSK1 (38% identical), PCSK2 (35% identical), PCSK7 (32% identical), MBTPS1 (18% identical), TPP2 (14% identical), PCSK9 (14% identical).
Diseases named in the same sentence as PCSK4 in open-access papers:
PCSK4 is named in the same sentence as 12 diseases in open-access papers, as found by Europe PMC text mining. Sharing a sentence is not in itself a finding about the gene and the disease. The quoted sentences say what the papers report.
endometrial cancer (2 papers, 2019 to 2020). Primary or metastatic malignant neoplasm involving the endometrium (mucous membrane that lines the endometrial cavity). "In another study, a six-gene prognostic signature, including CTSW, PCSK4, LRRC8D, TNFRSF18, IHH, and CDKN2A, in endometrial cancer was also established using robust likelihood-based survival modeling." (PMID 31781484, 2019).
aortic aneurysm (1 paper, 2022). A ruptured aneurysm located in the wall of the proximal portion of the descending aorta proceeding from the arch of the aorta. "Here we show that, with the exception of PCSK4, all other PCSKs genetically associate with various CVD-related phenotypes or traits, and several PCSKs are present on transcript and protein level in vascular biopsies from atherosclerosis and aortic aneurysm patients." (PMID 36188622, 2022).
Hypoglycemia (1 paper, 2023). A decreased concentration of glucose in the blood. "Ultimately, increasing levels of pro- and big-IGF2 suppress PCSK4 expression, and all together lead to a vicious cycle of high IGF2 and pro-IGF2 levels, triggering severe hypoglycemia." (PMID 37598269, 2023).
male infertility (1 paper, 2024). The inability of the male to effect fertilization of an ovum after a specified period of unprotected intercourse. "Three additional genes (PCSK4, AP3B1, and DLK1) were identified as novel relevant players in human male infertility using the gene-wise burden test approach (P < 5.56E−04)." (PMID 39678461, 2024).
tumor (2 papers, 2020 to 2021). "Meanwhile, increased expression of ST6GALNAC4 and PCSK4 was related to more sensitivity of tumor cells to a number of chemotherapy drugs like Temsirolimus, Bleomycin, Nelarabine, and Cladribine." (PMID 34970268, 2021). "The results showed that the expression levels of CORO1B, GOLGA7, PCSK4, ST6GALNAC4, and ZSWIM1 in normal tissues were significantly higher than those in tumor tissues, which were similar to the trends detected in the TCGA dataset." (PMID 34970268, 2021).
PCSK4 also shares sentences with these, for which no sentence is quoted: atherosclerosis (1 paper); cancer (1); colitis (1); intrauterine growth restriction (1); limb-girdle muscular dystrophy (1); oligospermia (1); spinal muscular atrophy (1).